PDGFRA (platelet derived growth factor receptor alpha)
Diseases named in the same sentence as PDGFRA in open-access papers (continued):
Sharing a sentence is not in itself a finding about the gene and the disease.
tumor (continued). "Even those tumours that lack genetic amplification of PDGFRA or PDGFRB still show strong expression of the genes associated with PDGFRA amplification, suggesting a central role for this pathway." (PMID 22771539, 2013). "GISTs are clinically and histologically heterogenous neoplasms that are driven by oncogenic KIT or PDGFRA mutations." (PMID 21559207, 2011). "Analysis at both the mRNA and protein level revealed that PDGFRα and PDGFRβ were consistently upregulated in tumor cells and tumor tissue following loss of IGF-IR expression." (PMID 22070644, 2011). "This difference of distributions is likely the consequence of the association of PDGFRA mutations with tumours of gastric origin." (PMID 20588273, 2010). "Seventeen tumours (16%) harboured PDGFRA mutations, 15 tumours originated from the stomach (14 with PDGFRA exon 18 and one PDGFRA exon 12), one from the peritoneum (omentum, PDGFRA exon 18 mutation) and one from the small bowel (PDGFRA exon 12 mutation)." (PMID 20588273, 2010). "The main reason for this shift is likely the gastric origin of most of the tumours harbouring PDGFRA mutations (15 of 17, 88%)." (PMID 20588273, 2010). "This analysis identified significantly lower expression of PKC-alpha and significantly higher expression of PKC-theta in tumours with KIT mutations compared to those with PDGFRA mutations or wild-type tumours." (PMID 19943934, 2009). "Overall, the results were concordant; however, we observed loss or gain of PDGFA and PDGFRA in recurrent tumours of some patients." (PMID 19707201, 2009). "We selected a model of gastric GIST to obtain a balanced set of tumours with mutations in either KIT or PDGFRA." (PMID 19943934, 2009). "Although mutations in KIT and PDGFRA contribute to tumour development through similar pathways, they correlate with certain clinicopathological features and different responses to imatinib treatment." (PMID 19943934, 2009). "Even though the biological consequences of KIT and PDGFRA mutations seem to be similar, our study has revealed hundreds of differentially expressed genes that group the tumours according to the receptor mutation status and receptor gene expression." (PMID 19943934, 2009). "Genotyping revealed that 15 tumours had KIT mutations (14 in exon 11 and one in exon 9), 11 tumours had PDGFRA mutations (9 in exon 18 and two in exon 12), and 3 were KIT/PDGFRA wild-type GISTs within the analyzed mutation hotspots." (PMID 19943934, 2009). "Of these 311 (FC>2), 109 probe sets (81 genes) were upregulated, and 202 probe sets (143 genes) were downregulated in samples from tumours harbouring KIT mutations compared to those with PDGFRA mutations." (PMID 19943934, 2009). "Many of these tumors have mutations in platelet-derived growth factor receptor alpha gene and a distinctive histomorphology characterized by myxoid epithelioid tumor cells and tumor infiltration by mast cells." (PMID 16092965, 2005). "In line with aggressive tumour behaviour, PDGFRA expression was also associated with high tumour grade and stage, large residual tumour size and high proliferation index." (PMID 15583695, 2004). "Both KIT and PDGFRA expression were associated with high tumour grade, high proliferation index and poor patient outcome." (PMID 15583695, 2004). "In addition, it highlights emerging challenges, including the management of polyclonal resistance, heterogeneity across KIT and PDGFRA mutations, and the need for dynamic monitoring of tumor evolution." (PMID 41517566, 2026). "Moreover, the mutation status of GISTs was shown to influence the tumour microenvironment, as PDGFRA-mutant GISTs reveal a specific immune profile that differs from GISTs with other mutations such as c-KIT." (PMID 41373613, 2025). "In addition, GISTs are characterized by mutations in the KIT or PDGFRA genes, leading to constitutive activation of tyrosine kinase receptors, which drive uncontrolled cellular proliferation and tumor progression." (PMID 40282558, 2025).
tumor (continued). "Furthermore, ripretinib shows efficacy against other tumor types harboring KIT or PDGFRA mutations, including mastocytosis, leukemia, and lung cancer." (PMID 40231257, 2025). "We could not find a correlation between the establishment of a model and the type of mutation (primary KIT versus secondary KIT versus PDGFRA versus other mutations) of the tumor sample." (PMID 39853155, 2025). "The same analysis also revealed an independent association between GIST genotype and tumor primary size (OR for >10 vs <5 cm, 7.91 [95% CI, 1.90-32.84]; P = .004), confirming the association among the presence of a PDGFRA mutation, stomach as the primary site, and a greater tumor size." (PMID 39853981, 2025). "Moreover, the triad of gastric primary tumor, tumor size greater than 10 cm, and SUVmax of 5.75 or less was associated with identification of PDGFRA-mutant GISTs." (PMID 39853981, 2025). "Pdgfrα+ CAFs presented high levels of PDGFRα and inflammation-associated genes, which might play important roles in the inflamed tumour microenvironment." (PMID 39827226, 2025). "Thus, PCTSs from tumours with c-KIT mutations were considered imatinib-sensitive, while PCTSs from tumours with PDGFRA mutations were expected to be imatinib-resistant." (PMID 41373613, 2025). "If feasible, gene sequencing can be performed to detect c-kit or PDGFRA mutations in tumor cells." (PMID 40356746, 2025). "With L-PCR, tumour-specific cKIT or PDGFRa mutations were found in cfDNA of 16/25 patients." (PMID 39797974, 2025). "Therefore, the wild-type genetic status for both KIT and PDGFRA was included as a required tumor parameter in the INT2GRATE|HPPGL Variant Evidence Framework." (PMID 38473309, 2024). "In addition to these studies above, mostly implying PDGFRβ as the key receptor, other studies have linked PDGFRα to tumor-restraining effects." (PMID 38980580, 2024). "Additionally, the GDA (Gene-Disease Association) scores for these genes, particularly PDGFRA with a score of 0.75, provide strong evidence linking them to cellular proliferation and tumor growth." (PMID 39606019, 2024). "We also found that the shared copy number variants (CNVs) between CSF and tumor tissue, including PDGFRA, MDM2, CDK4, and others, were exclusively observed in DMG, H3K27-altered, and the copy number value of shared CNVs showed a strong correlation between CSF and tissue." (PMID 38388726, 2024). "Second, the data in this study came from the Seer database, and some of the variables lacked details, such as the specific type of surgery, the size and number of liver metastases, the detailed chemotherapy regimen and dose, chemotherapy responsiveness, and tumor KIT or PDGFRA mutation information." (PMID 38347834, 2024). "Using scRNA-seq on tumor samples and para-tumor samples from bladder carcinoma and the sequencing data from TCGA, investigators found that the iCAF-specific marker PDGFRA was associated with poor overall survival while the myo-cancer-associated fibroblast marker RGS5 was not." (PMID 36830713, 2023). "In 15 out of 38 plasmas from GIST patients harboring c-KIT or PDGFRA mutations in tumor tissues, Maier and colleagues identified ctDNA (circulating tumor DNA) bringing tumor-specific mutations, by the allele-specific Taq-Man duplex PCR allele-specific ligation PCR technique." (PMID 37046997, 2023). "According to our limited data, GIST patients with both ALK expression and PDGFRA mutation tend to have a larger tumor diameter, higher recurrence risk and more mitotic figures, indicating that ALK expression may be associated with a worse prognosis." (PMID 37120571, 2023). "It has been shown that PDGFRA is involved in gene mutation, tumor cell proliferation, migration and invasion, maintenance of mesenchymal stromal cells (MSC), and immune infiltration, while it may serve as a potential biomarker and therapeutic target." (PMID 35212838, 2022).
tumor (continued). "Gain-of-function PDGFRA variants trigger multiple tumor-promoting signaling cascades, including phospholipase Cγ (PLCγ), phosphatidylinositol-3-kinase (PI3K), mitogen-activated protein (MAP) kinase, and signal transduction and Activators of Transcription (STATs)." (PMID 35109850, 2022). "However, the increased expression of phosphorylated-PDGFRα after the genome editing indicates a certain potential of this mutation for tumor proliferation or carcinogenesis." (PMID 35075231, 2022). "(d) Reverse the tumor progression caused by the increased expression of PDGFRA caused by RT." (PMID 35497337, 2022). "Furthermore, in one exophytic gastric lesion with a PDGFRA mutation, the fluorescence intensity was found to be relatively specific for the tumor tissue, in the qualitative assessment." (PMID 35326721, 2022). "The mutation status of KIT and PDGFRA, together with the tumor location, tumor size, and mitotic count, are prognostic factors and aid in clinical decisions on whether to offer medical oncological treatment to the patients before and after surgery." (PMID 36497235, 2022). "Together, our results revealed that the PTEN-AKT1-CREB-PDGFRα signaling pathway may exist in human tumors and the high expression of PDGFRα was associated with poor prognosis in tumor patients." (PMID 33568640, 2021). "Our aims were to comprehensively analyze genomic changes in Chinese GISTs and to identify rare novel gene mutations in KIT/PDGFRA or other tumor-related genes that may take part in the development and chemoresistance of GIST from an omics viewpoint." (PMID 34805171, 2021). "In addition, patients with KIT mutated GISTs tended to have an increased tumor size and a higher mitotic index and risk grade as compared with those with PDGFRA and WT-mutated GISTs." (PMID 34956906, 2021). "In many patients with eosinophil-rich neoplasms, a mutation in PDGFRA or PDGFRB is detected." (PMID 34052871, 2021). "We investigated the expression of human PDGFRα because it is recognized as marker of tumor RMS cells, while the variant β (human PDGFRβ) was primarily detected in vascular stroma and it has been shown to be more related to wound healing and leukocyte differentiation." (PMID 33585217, 2020). "It is possible, however, that multiple mutation events resulting in EGFR and PDGFRA amplification in cells could be occurring in an evolving tumour and it may be more appropriate to model such single cell events in a micro- or meso-scopic setting." (PMID 33120534, 2020). "Mild to moderate nuclear atypia was significantly associated with KIT exon 11 (100%) and exon 9 mutations (100%) whereas 37.5% cases with PDGFRA exon 18 mutation and 15% of wild type GISTs showed severe atypia including plasmacytoid cells and binucleate tumour giant cells (p=0.01)." (PMID 31538651, 2020). "In recent years, some studies show that IFP is a benign tumor with PDGFRA gene activation mutation." (PMID 32258417, 2020). "However, for GIST patients with tumours harbouring a D842V mutation in PDGFRA exon 18, avapritinib has shown efficacy and will become first-line therapy for this molecular subgroup." (PMID 32462367, 2020). "Another factor that could result in some biopsies having only EGFR and others only PDGFRA amplified is that the mutations occurred in different places, resulting in the populations occupying different, spatially separated regions of the tumour." (PMID 33120534, 2020). "Also, in EGIST, the degree of KIT and PDGFRA mutations varies on where the location of the tumor is." (PMID 32703220, 2020). "However, in cases with a risk of recurrence and cases of progressive GIST, KIT and PDGFRA genotyping is important for the assessment of drug sensitivity and tumor aggressiveness." (PMID 31410732, 2019). "Additionally, PDGFRA expression has been associated with more aggressive tumor phenotypes and increased metastatic potential." (PMID 31331295, 2019).
tumor (continued). "Furthermore, the levels of expression of mutant PDGFRA or NTRK fusion genes expressed in the mouse HGGs are relevant to the levels of expression found in human tumor cells with these mutations." (PMID 31420543, 2019). "Thus, extracellular domain mutations in PDGFRA have the potential to alter both proliferation and migration, key components of tumor pathophysiology." (PMID 30389923, 2018). "Although KIT and PDGFRA mutations are likely of key importance in the molecular pathogenesis of GISTs, identical single KIT or PDGFRA mutations may be associated with widely different tumour mitotic counts and GIST patient survival outcome." (PMID 29377440, 2018). "High tumour cell PDGFRα expression has been linked to lymph node metastasis, human epidermal growth factor receptor 2 (HER2) positivity, high histologic grade, oestrogen receptor (ER) negativity, progesterone receptor (PR) negativity and the triple-negative breast cancer subtype (TNBC)." (PMID 29380207, 2018). "The exact mechanism of PDGFRα in vasculogenesis and tumor angiogenesis is yet unknown, but an overexpression of PDGFRα caused by gene amplification may result in more aggressive tumor growth." (PMID 28484518, 2017). "Interestingly, overexpression of wild-type PDGFRA was even more detrimental than an activating mutation in PDGFRA leading to a tumor incidence of 80 vs. 50% at 30 weeks." (PMID 28894696, 2017). "Previous studies showed that sorafenib could inhibit the proliferation of cell lines or patient’s tumor with PDGFRA mutation." (PMID 27105424, 2016). "However, GISTs with a PDGFRα mutation most commonly arise in the stomach, and the tumor is typically DOG1-positive." (PMID 27842558, 2016). "Tumour genotyping revealed a mutation on exon 18 of the PDGFRα gene, excluding the D842V mutation." (PMID 25202412, 2014). "Therefore, we examined associations between 522 single nucleotide polymorphisms and seven KIT or PDGFRA tumor mutations types." (PMID 24159917, 2013). "Loss of function of PDGFRα through siRNA or imatinib induced tumor cell apoptosis." (PMID 21253475, 2011). "It is noteworthy that although 57% of the tumours with PDGFRA mutations in our series were classified as intermediate or high risk according to the NIH consensus, most of these tumours were classified as low or very low risk according to the AFIP risk classification." (PMID 20588273, 2010). "PDGFRβ is expressed in a significant higher number of tumor-associated stromal cells than PDGFRα." (PMID 27713269, 2010). "Two recent autopsy series have shown that the incidence of GIST may be as high as 50% in stomach specimens; in one of these series, canonical KIT or PDGFRA mutations were found in 50% of assessable tumours." (PMID 20588273, 2010). "Of these, 13 and 8 tumours had KIT or PDGFRA mutations, respectively." (PMID 19943934, 2009). "PDGFRα has been linked to poor prognosis and aggressive tumor characteristics." (PMID 19112514, 2008). "Activating mutations of the genes c-kit and PDGFRα characterize the tumor entity GIST." (PMID 18651966, 2008). "Interestingly, the lowest SCF amount was found in a tumour in which PDGFRA mutation had been detected." (PMID 16570044, 2006). "GISTs are usually characterized by gain-of-function mutations in either the KIT or PDGFRA genes, leading to constitutive, ligand-independent activation of the respective receptor tyrosine kinases and downstream signaling pathways, resulting in uncontrolled tumor cell proliferation." (PMID 40590035, 2025). "Therefore, an increased area under the curve and peak intensity on CEUS might reflect increased tumor angiogenesis and perfusion related to mutations in PDGFRA." (PMID 37120792, 2023).
tumor (continued). "However, the tumor cells exhibited systemic PDGFRA mutations in our study." (PMID 37454137, 2023). "To investigate the in vivo effect of PDGFRα on the tumoral growth of Pten-deficient cells, we injected Pten-deficient MEFs expressing shPDGFRα or shScramble subcutaneously into the right anterior armpit of nude mice, and tumor growth was monitored for 30 days post-injection." (PMID 33568640, 2021). "Most inflammatory fibroid polyps bear PDGFRα-mutations (PDGFRα is one of the typical antigens of telocytes of the gastrointestinal tract), so in this case the designation “telocytoma” properly represents not only the genuine neoplastic nature of this tumor, but also its plausible histotypic lineage." (PMID 30781716, 2019). "Thus, downregulated FOXO3a/PDGFRα/AKT pathway may serve as a protective mechanism against TSC-associated tumor development." (PMID 28903387, 2017). "Interaction of PDGF-C with PDGFRα promotes tumour growth by several mechanisms, acting as: survival and mitogenic factor for tumour cells, mitogenic and chemoattractant factor for cancer-associated fibroblasts and inducer of tumour angiogenesis in a VEGF-A-independent way." (PMID 28977999, 2017). "We had previously reported an association of post-irradiated HGG with PDGFRA amplification and chromosome 1q gain, so it appears these are relatively selective radiation-induced changes, rather than reflecting a generalised genomic instability in secondary tumours from these patients." (PMID 24548782, 2014). "In addition to KIT/PDGFRA mutational status, our findings indicate that secondary chromosomal changes contribute significantly to tumor development and progression of GIST and that genomic complexity carries independent prognostic value that complements clinico-pathological and genotype information." (PMID 20470368, 2010). "Moreover, tumor shrinkage could be observed even in cases with less favorable KIT/PDGFRα mutational status, with an overall median tumor reduction of 34%." (PMID 19646278, 2009). "Therefore, detection of a PDGFRA mutation in gastric GISTs may represent an additional prognostic marker of more benign tumour behaviour." (PMID 18253129, 2008). "Targeted therapies for PDGFRA and PIK3CA mutations can control tumor growth and metastasis but face challenges like drug resistance and high costs." (PMID 41799769, 2026). "By directly inhibiting mutant-driven oncogenic signaling, avapritinib suppresses cell proliferation, promotes apoptosis, and reduces tumor vascular support indirectly, given that PDGFRA-mutant tumors often induce pro-angiogenic microenvironments." (PMID 41517566, 2026). "Crucially, vaccine-based therapeutic modalities targeting PDGFRA offer a compelling dual strategy: they hold the potential to suppress tumor proliferation while simultaneously reversing immune evasion mechanisms." (PMID 41847712, 2026). "Targeted therapies for PDGFRA and PIK3CA mutations control tumor growth but face drug resistance and cost issues." (PMID 41799769, 2026). "One was a PDGFRA-mutated GIST, and from one model the clinical information about mutational status of the tumor sample was missing." (PMID 39853155, 2025). "For instance, numerous preclinical studies are being conducted to evaluate targeting of tumor-associated factors, such as fibroblast growth factor receptor 1 protein (FGFR1), platelet-derived growth factor receptor alpha (PDGFRA), and VEGF receptor 2 (VEGFR2)." (PMID 41219972, 2025). "Multi-plex IHC confirmed co-localization of RUNX1 with FAP protein at the tumor core and USF2 with PDGFRA expression at the tumor margin." (PMID 39870619, 2025). "Genotypically, most GISTs are driven by activating mutations in the tyrosine kinase receptors, KIT and platelet-derived growth factor receptor alpha (PDGFR-α), leading to uncontrolled cell proliferation and tumor growth." (PMID 40417261, 2025). "Consistent with the in vitro findings, a significant upregulation of PDGFRA was also detected in the tumor specimens." (PMID 40336047, 2025).